TNF (tumor necrosis factor)
Diseases named in the same sentence as TNF in open-access papers (continued):
Sharing a sentence is not in itself a finding about the gene and the disease.
depression (continued). "However, further research is required to investigate and validate these hypotheses, shedding light on the relationships between neuroinflammation, A1 astrocytes, TNF-α, and depression." (PMID 38710713, 2024). "Therefore, individuals with depression and periodontitis appear to share an alteration in the production of various pro-inflammatory factors (IL-1, IL-6, TNF-α), which, on the one hand, increases the individual’s systemic inflammatory load and, on the other hand, increases neuroinflammation." (PMID 39124790, 2024). "Additionally, BPF exhibits antidepressant effects by reducing levels of arginine vasopressin in the pituitary, decreasing the expression of arginine vasopressin mRNA in the hypothalamus and increasing plasma tumor necrosis factor-α levels in menopausal patients with depression." (PMID 38921335, 2024). "Even though elevated TNF is implicated in the development of neuroinflammation, particularly in the context of neurodegenerative diseases and depression, psilocin may not be effective at suppressing the production of this cytokine by microglia." (PMID 39519725, 2024). "The last hypothesis of depression regards inflammation, according to which, the development of depression is accompanied by increased levels of proinflammatory cytokines, such as interleukin-1β, interleukin-6, and tumor necrosis factor alpha (TNF-α)." (PMID 39201362, 2024). "Furthermore, individuals with depression have significantly higher levels of inflammatory cytokines, such as interleukin-1 (IL-1), interleukin-4 (IL-4), interleukin-6 (IL-6), and tumor necrosis factor-alpha (TNF-α), which are also important mediators in the pathogenesis of asthma." (PMID 39479594, 2024). "Furthermore, we showed that Rho may alleviate depression by decreasing the expressions of TNF-α and TNFR1." (PMID 38710713, 2024). "IL-6 and TNF-α may also compromise the blood–brain barrier in depression." (PMID 38541828, 2024). "Furthermore, higher serum levels of tumor necrosis factor (TNF)α as well as lower levels of brain-derived nuclear factor (BDNF), were found in depressive patients, with an association between BDNF levels and the severity of the depression." (PMID 38796643, 2024). "However, the role of A1-type astrocytes activated by TNF-α in depression is currently unclear." (PMID 38710713, 2024). "Interestingly, 2-AG and AEA have shown anti-inflammatory activity by down regulating inflammatory cytokines such as TNF-α, suggesting that the ECS may play a role in modulating neuroinflammation associated with depression." (PMID 38886733, 2024). "Furthermore, TNF‐α antagonists have shown antidepressant and pro‐cognitive effects in mouse models, providing additional insights into the potential therapeutic relevance of targeting inflammatory pathways in the context of depression." (PMID 39236111, 2024). "The main question is whether plasma concentrations of pro-inflammatory cytokines (IL-6, IL-1α, and TNF-α) can serve as predictive biomarkers for depression severity and whether these concentrations are modulated by gender among patients diagnosed with major depressive disorder (MDD)." (PMID 39595067, 2024). "Thus, we assumed that A1 astrocytes were activated by TNF-α during depression." (PMID 38710713, 2024). "Additionally, icariin downregulates the serum levels of IL-6 and TNF-α in rats with depression." (PMID 38915473, 2024). "Unlike clinical research results, our study revealed no causal relationship between ss and depression and anxiety from a genetic perspective, maybe elevated IL-1, IL-6, TNF-α and IFN-α levels are not related to the pathogenesis of SS." (PMID 39479595, 2024). "Elevated serum levels of miR-9-5p in individuals with depression stimulate the polarization of M1 microglia, triggering excessive release of pro-inflammatory cytokines such as interleukin-1β (IL-1β), interleukin-6 (IL-6), and tumor necrosis factor-α (TNF-α), thereby exacerbating neurological damage." (PMID 38528957, 2024).
depression (continued). "In addition, baseline TNF-α might predict middle-term suicidal ideation and behavior in depression patients." (PMID 38459460, 2024). "Besides RA, IL-6, IL-17, and TNF-α also increase in malignancy conditions, including colorectal cancer, breast cancer, and pancreatic cancer, which implicates the pathogenesis of anxiety and depression." (PMID 37916198, 2023). "Patients with anxiety and depression present inflammatory response with an increase in the serum concentration of pro-inflammatory cytokines, such as interleukins (IL)-6, tumor necrosis factor (TNF), IL-12, IL-13, and IL-18, between other mediators, including C-reactive protein (PC-R)." (PMID 37513187, 2023). "Furthermore, p-Coumaric acid (p-CA), a polyphenol, has decreased inflammatory molecular alterations like TNF-α, suggesting it may be helpful as an alternate treatment for refractory depression." (PMID 37368609, 2023). "However, further studies are needed to validate the potential benefit of a TNF-α antagonist for treatment of depression in patients with RA, which could be driven by inflammatory cytokines." (PMID 37346903, 2023). "Interestingly, the tears of patients with depression showed higher levels of inflammatory cytokines IL-6, IL-17 and TNF-a, which may take part in dry eye inflammation." (PMID 36674068, 2023). "The cytokine hypothesis suggests that in depression, the number of pro-inflammatory cytokines such as IL-6, IL-1β and TNF-α is increased, while the number of anti-inflammatory cytokines such as IL-10 and TGF-β is decreased, tilting the overall immune response toward inflammation." (PMID 37387537, 2023). "Additionally, including other pro- and anti-inflammatory markers beyond TNF-α and IL-10 could provide a more comprehensive understanding of the inflammatory processes in depression." (PMID 37680396, 2023). "Indeed, other studies have found that depression is associated with both CAD and cognition and increases the risk of developing CAD, likely due to its pro-inflammatory state with increased levels of IL-1, IL-6 and TNF-alpha." (PMID 37627038, 2023). "Notably, MSCs have the ability to downregulate the expression of the proinflammatory cytokines IL-1β, IL-6, and TNF-α, which is one of the major reasons that contribute to the development of depression, as discussed in the cytokine hypothesis." (PMID 36986674, 2023). "Moreover, TNF‐α is positively correlated with depression in myocardial infarction patients." (PMID 37878890, 2023). "In addition, we speculate that the effects of on depression could relate to the decrease in the proinflammatory cytokines including TNF‐α." (PMID 36178333, 2023). "Additionally, studies have examined interleukin and TNF-α levels in depression." (PMID 37680396, 2023). "There is evidence that depressive disorder is characterized by increased activity of immune cells and increased levels of proinflammatory cytokines, especially pivotal cytokines such as interleukin (IL)-1β, IL-6, tumor necrosis factor (TNF)-α, and interferon (IFN)-γ." (PMID 37834806, 2023). "Therefore, pro-inflammatory cytokines, including IL-1, IL-6, and TNF-α, may cause 5-HT synthesis deficiency by activation of the tryptophan metabolizing enzyme IDO, and finally lead to depression." (PMID 36686689, 2022). "Pro-inflammatory cytokines, e.g., IL-1β, IL-6, TNF-α, and acute phase proteins, were described to be increased in experimental animal models of chronic stress-induced depression as well as in patients with major depressive disorder (MDD) compared to healthy controls." (PMID 36014842, 2022). "In a chronic mild stress model of depression, mice receiving a three-strain probiotic blend, Lactobacillus helveticus, Lactobacillus plantarum, and Bifidobacterium longum, displayed improved depression-like behavioral responses accompanied by a reduced TNF-α and interferon (IFN)-γ levels." (PMID 35546876, 2022).
depression (continued). "In line with the immunometabolic hypothesis, studies have shown that genetic polymorphisms in inflammatory genes such as interleukin 1 beta (IL-1β), tumor necrosis factor alpha (TNFα) and C-reactive protein, influence depression incidence, severity, and treatment response." (PMID 35422688, 2022). "Nonetheless, a recent systematic review and meta‐analysis revealed that neither the genotypes of the TNF‐α G308A gene nor allele frequencies might represent an independent risk factor of depression." (PMID 34590391, 2022). "Furthermore, animal experimental results showed that TNF-α produced a depression-like state in mice reinforcing the idea that inflammatory components may play a crucial role in the pathophysiology of depressive symptoms." (PMID 36685498, 2022). "Therefore, NLRP3 inflammasome-mediated microglia activation, and the secretion and release of TNF-α, IL-1α, and PGE2, may be major causes of depression-like behavior." (PMID 36421482, 2022). "The second major finding of this study is that depression is accompanied by increased production of the Th-1, Th-2, Th-17, and Treg cytokines and partial activation of the M1 phenotype (increased production of TNF-α, sIL-1RA, and CXCL8) as compared with healthy controls." (PMID 35455402, 2022). "The reduced SDS scores and improved depression state in the ESWT group compared with the control group may be associated with analgesic effects and neuroinflammatory alterations caused by ESWT, such as TNF-α, which could be explored in further study." (PMID 36226089, 2022). "Two mechanisms may link TNF-α to the pathophysiology of depression." (PMID 35722555, 2022). "In addition, pro-inflammatory cytokines and immune cell pathways such as IL-17, TNF, B cell receptor, and T cell receptor signaling pathway were identified, indicating that inflammation plays a key role in the onset and development of depression." (PMID 36325528, 2022). "Depression symptoms are associated with increased levels of TNFα; in students, moderate intensity, continuous PE decreased depressive symptoms, perceived stress and TNFα levels compared to healthy students with no exercise." (PMID 35328666, 2022). "Inflammatory cytokines such as IFN-γ and TNF-α may trigger depression in humans." (PMID 36354670, 2022). "TNF-α might contribute to the pathogenesis of depression by activation of the HPA axis." (PMID 36686689, 2022). "A wide variety of proinflammatory cytokines, such as IL-1β, IL-2, IL-6, IL-12 and tumor necrosis factor (TNF-α), in addition to some antibodies (ribosomal antibody-P and anti-N-receptor methyl-D-aspartate) interfere in the mediation of the inflammatory processes of depression." (PMID 35268082, 2022). "Therefore, it could be concluded that the level of TNF-α in the peripheral blood of patients with depression is higher than that of control." (PMID 34421539, 2021). "Clinical studies have indicated that patients suffering from depression showed significantly higher levels of proinflammatory cytokines, including interleukin-1β (IL-1β), interleukin-6 (IL-6), tumor necrosis factor alpha (TNF-α), C-reactive protein (CRP), and inflammasome, than healthy people." (PMID 33466877, 2021). "Moreover, TNF-α and IL-1β may bind with the peripheral afferent nerve fibers, which in turn stimulate ascending catecholaminergic fibers in the brain to affect depression." (PMID 34827513, 2021). "Interestingly, TNFα levels are positively correlated with midbrain serotonin transporter (SERT) availability in humans, suggesting a possible immunomodulatory mechanism that underlies dysregulated serotonin neurotransmission in depression." (PMID 33935636, 2021). "More precisely, MDD had increased IL-1β, tumor necrosis factor α (TNF α), sTNFR 1, IL-12 and IL-10 while BD depression was characterised by an increase in IL-6, sTNFR 2, IL-18, IL-33, ST2, and KLOTHO." (PMID 33946871, 2021).
depression (continued). "However, there are other cytokine (e.g., interleukin-1, tumor necrosis factor-alpha) which might better reflect allostatic changes in depression and CAD." (PMID 33801190, 2021). "In the mITT analysis, TNFα showed a non-significant interaction with group, with higher levels associated with more severe depression at post-treatment in metyrapone than placebo groups (β = 8.24 [95% CI −1.59, 18.01], standardised effect size (SES) = 0.36, p = 0.097)." (PMID 33669254, 2021). "Our findings on the TNF modulation of in utero hippocampal development in the context of maternal depression during pregnancy provide new inflammatory markers that can be potentially considered as one of the inflammation-targeted therapies for depression, particularly during pregnancy." (PMID 32688365, 2021). "Indeed, TNFα has been implicated in major depressive disorder but has not yet been evaluated therapeutically in patients with this disorder." (PMID 34511110, 2021). "The expression levels of TNF-α (p < 0.01), IL-6 (p < 0.05), and IL-1β (p < 0.01) in the CUMS group were significantly higher than those in the control group, which indicated that the occurrence of depression was associated with the production of inflammatory factors." (PMID 35185541, 2021). "Hence, TNF-α could be a valuable marker of treatment resistance (a treatment-response marker) and a potential new biological target for the pharmacotherapy of depression." (PMID 33255237, 2020). "However, some other inflammatory markers relevant to depression were either increased only at 24 h (hsCRP, IL-8) or increased at all timepoints, including 24 h (TNF-α), indicating that systemic inflammatory processes were still present at the time of the second scan." (PMID 32152285, 2020). "High levels of IL-1β, IL-2, and TNF-α can induce neuronal apoptosis, inhibit neuronal differentiation, abolish synaptic transmission, and counteract either the induction or maintenance of long-term potentiation, thus leading to an impairment of learning and further worsening of depression symptoms." (PMID 32849818, 2020). "Adipose tissue produces inflammatory factors, including cytokines such as IL-6, TNF-α, and chemokines, which in turn may activate widespread immune reaction, potentially leading to or exacerbating inflammation-related diseases, including depression." (PMID 32140686, 2020). "Research has indicated that during the development of chronic neuropathic pain, persistent noxious stimuli could result in an increase in TNF-α in the hippocampus, which then disrupts the depression-related brain circuit of hypothalamic-pituitary-adrenal axis dysfunction." (PMID 32241292, 2020). "In addition, microglial injury may lead to depression, and drugs that inhibit microglial activation, such as minocycline and tumor necrosis factor alpha (TNF-α) inhibitors, are also considered effective antidepressants." (PMID 32367473, 2020). "Thus, the allele frequencies and genotypes might be connected with the level of TNF‐α instead of the depression." (PMID 32307924, 2020). "In summary, neither the allele frequencies nor genotypes of TNF‐α G‐308A gene could be served as an independent risk factor of depression." (PMID 32307924, 2020). "Finally, given the potential role of inflammation in the relationship between AS and depression, treatments for AS, particularly anti-tumour necrosis factor (anti-TNF) agents, may also impact depression as suggested in prior clinical study." (PMID 32159073, 2020). "Neither the allele frequencies nor genotypes of TNF‐α G‐308A gene could be served as an independent risk factor of depression." (PMID 32307924, 2020). "In line with our expectations, the levels of the pro-inflammatory cytokines TNF-α, IL-1β, and IL-6 were decreased after the ketamine infusions in our study, which is consistent with the results of previous studies that administered a single infusion in patients with depression." (PMID 32699226, 2020).
depression (continued). "Pro-inflammatory cytokines such as interferon-gamma (IFNγ) and tumour necrosis factor-alpha (TNFα) might affect the progress of depressive disorder by regulating neuronal excitability, synaptic transmission, synaptic plasticity, excitotoxicity and neuronal survival." (PMID 33322180, 2020). "The currently available data do not justify a hypothesis that early-life adversity and the TNF-α SNP would be associated with adult depression, but this SNP was included in the present analysis to replicate previous null findings." (PMID 30967802, 2019). "More recently, an abundance of experimental evidence suggests that activation of innate immune mechanisms, especially tumor necrosis factor alpha, proinflammatory cytokines, and C-reactive protein, may contribute to psychiatric disease pathology such as depression." (PMID 31647818, 2019). "Although there have been several reports indicating that inflammatory factors, notably circulating IL-6 and TNF-α, were associated with major depressive illness, as previously observed, the IL-6 rs1800795 SNP was not directly related to depression scores in the present study." (PMID 30967802, 2019). "In the analysis of other explanatory variables in the final model, there were positive significant associations with CRF for anxiety (β = 0.74, P < 0.001) and depression (β = 1.06, P < 0.001) and significant negative associations for TNF‐α (β = −0.009, P < 0.001) and age (β = −0.23, P = 0.004)." (PMID 31016867, 2019). "Additionally, it has been hypothesized that external stressors may induce depressive disorders via stimulation of inflammatory, oxidative, and apoptotic mechanisms, closely related to the pathways, such as TNF-α, NF-κB, Toll-like receptor, and apoptosis." (PMID 31275757, 2019). "Additionally, cytokines, such as TNFα, also can disrupt BBB permeability, raising the possibility that increased BBB permeability caused by microglia-derived cytokines contributes to depression by promoting the infiltration of peripheral inflammatory molecules and immune cells." (PMID 30174579, 2018). "Therefore, a reduction of TNF-α could be beneficial for ameliorating symptoms of anxiety and depression, as is the case with other antidepressant agents." (PMID 29623232, 2018). "TNF application further mediates activation of microglia, which may result in a self-perpetuating loop of neuroinflammatory disturbance resulting in depression-like behavior." (PMID 30057531, 2018). "For example, elevated levels of interleukin (IL) IL-1β, IL-6, tumor necrosis factor alpha (TNFα) and C-reactive protein (CRP), and of corticotrophin releasing hormone (CRH) and cortisol, have all been described in association with antenatal symptoms of depression." (PMID 30033161, 2018). "Moreover, Maes and fellow workers have established an association between the presence of functional SNPs in TNF-α, IL-1β and CRP and an increased risk of developing depression and, indeed, responsiveness or otherwise to the administration of antidepressant therapy." (PMID 29294244, 2018). "The identification of higher NIHSS scores, higher HAMD scores, lower dopamine level, lower 5-hydroxytryptamine level, higher tumor necrosis factor-α level, and lower nerve growth factor level might be useful for clinicians in recognizing and treating depression in patients after a stroke." (PMID 29149884, 2017). "Consequently, medications that result in lower IL-6 and TNF-α level might have a direct positive impact on treating depression." (PMID 30886949, 2017). "Increased IL-6 and TNF-α levels may promote depression by downregulating serotonin metabolism." (PMID 28930237, 2017). "Increased IL-6 and TNF-α levels may also promote depression by downregulating serotonin metabolism." (PMID 28930237, 2017).